ARHGDIB (Rho GDP dissociation inhibitor beta)
Description:
Regulates the GDP/GTP exchange reaction of the Rho proteins by inhibiting the dissociation of GDP from them, and the subsequent binding of GTP to them. Regulates reorganization of the actin cytoskeleton mediated by Rho family members.
Synonyms: GDIA2; GDID4; RAP1GN1; Ly-GDI; RhoGDI2; D4; LYGDI
Tractability: Small molecule: a structure with a bound ligand is known; it has a binding pocket of medium quality. PROTAC: ubiquitination databases record sites on it; its protein half-life has been measured.
Gene: Protein-coding gene on chromosome 12 (14,942,015 to 14,961,985, reverse strand). Ensembl gene ENSG00000111348.
Subcellular location: Cytoplasm, cytosol
Subcellular location (Human Protein Atlas): Cytosol
Pathways (Reactome):
Signal Transduction: CDC42 GTPase cycle; RAC1 GTPase cycle; RAC3 GTPase cycle; RHOA GTPase cycle; RHOG GTPase cycle; RHOH GTPase cycle
Gene Ontology:
Molecular function: GTPase activity; protein binding; Rho GDP-dissociation inhibitor activity; small GTPase binding
Biological process: negative regulation of trophoblast cell migration; regulation of Rho protein signal transduction; Rho protein signal transduction; cellular response to redox state
Cellular component: cytosol; extracellular exosome; cytoplasm; cytoplasmic vesicle; cytoskeleton; membrane
Genetic constraint (gnomAD): Loss-of-function variants: 9 observed, 17.83 expected, observed/expected ratio (o/e) 0.5, 90% interval 0.3 to 0.88. The upper end of that interval is the gene's LOEUF score, 0.88, which puts it in group 3 of 6, group 1 being the genes least tolerant of losing a copy. Missense variants: 213 observed, 217.07 expected, observed/expected ratio (o/e) 0.98, 90% interval 0.88 to 1.1. Synonymous variants: 99 observed, 86.32 expected, observed/expected ratio (o/e) 1.15, 90% interval 0.97 to 1.36.
Homologues: Orthologues: chimpanzee ARHGDIB (100% identical), macaque ARHGDIB (99% identical), dog ARHGDIB (94% identical), pig ARHGDIB (93% identical), guinea pig ARHGDIB (90% identical), rabbit ARHGDIB (89% identical), mouse Arhgdib (87% identical), rat Arhgdib (86% identical), tropical clawed frog arhgdib (77% identical), Drosophila melanogaster RhoGDI (49% identical), Caenorhabditis elegans rhi-1 (40% identical). Paralogues in human: ARHGDIA (69% identical), ARHGDIG (56% identical).
Diseases named in the same sentence as ARHGDIB in open-access papers:
ARHGDIB is named in the same sentence as 58 diseases in open-access papers, as found by Europe PMC text mining. Sharing a sentence is not in itself a finding about the gene and the disease. The quoted sentences say what the papers report.
gastric cancer (20 papers, 2013 to 2025). A primary or metastatic malignant neoplasm involving the stomach. "ARHGDIB has been found to function as a positive regulator of cancer progression in ovarian, breast, colorectal and gastric cancers, and as a negative regulator in Hodgkin's lymphoma, bladder cancer and lung cancer." (PMID 34184409, 2021). "Divergent roles for ARHGDIB have subsequently been proposed in the literature with some evidence for a role in the suppression of metastasis in bladder cancer and in contrast a proinvasive role in gastric cancer." (PMID 28336725, 2017). "PAK2 was a necessary interaction partner of ARHGDIB, and knockdown of PAK2 greatly reduced ARHGDIB-induced cell invasion and ARHGDIB-mediated chemoresistance in gastric cancer, and loss of SATB1 in lung cancer has been shown as a possible marker for poor survival." (PMID 24369726, 2013).
bladder cancer (19 papers, 2007 to 2024). "Previous study reported that ARHGDIB, also known as RhoGDI2, is a guanosine diphosphate dissociation inhibitor that can decrease cell migration and invasion in bladder cancer." (PMID 36941989, 2023). "For example, the ATG7 gene, which is overexpressed in invasive bladder cancer tissue, can promote autophagic degradation of the HNRNPD (ARE/poly(U)-binding/degradation factor 1) protein, which, in turn, increases ARHGDIB mRNA stability and bladder cancer cell invasion." (PMID 36875752, 2023).
breast carcinoma (15 papers, 2009 to 2024). "In summary, validation analysis using RT-PCR and DNA sequencing successfully identified variants 6a, 6b, and 6c—3 novel splice variants of the ARHGDIB gene—in colon, pancreas, stomach, and breast cancer cell lines; these variants were also found to be highly expressed in normal placental tissue." (PMID 23206989, 2012). "Of note, ARHGDIB up-regulation has also been reported from breast cancers where it promotes invasiveness." (PMID 31557128, 2019). "ARHGDIB is known to be involved in the progression of metastasis in colon, pancreas, stomach, and breast cancer." (PMID 23206989, 2012). "ARHGDIB can mediate epithelial-mesenchymal transition through the downstream effector MMP-2 as high expression of this gene is indicative of a poor prognosis in breast cancer patients." (PMID 38447798, 2024). "ARHGDIB overexpression in tumor cells is associated with tumor growth and metastasis in different cancers and positively correlates with tumor size, lymph node metastasis, and TNM stage in breast cancer patients." (PMID 36143471, 2022). "Moreover, ARHGDIB depletion leads to decreased proliferation, migration, and invasion of breast cancer cells." (PMID 36143471, 2022). "High ARHGDIB expression is the indicator of poor prognosis in breast cancer patients." (PMID 36143471, 2022). "Importantly, previous reports have demonstrated that inhibition of ARHGDIB in invasive breast cancer cell lines significantly reduces their invasive behavior through regulation of β1-integrin signaling." (PMID 19257890, 2009). "A decrease in the transcription levels of human invasion signature (HIS) genes (ARHGDIB, CAPZA2, PHACTR2, CDC42, XRCC5, and CAV1) has been also demonstrated by real-time PCR, with high expression of these genes being a hallmark of actively metastasizing breast cancer cells." (PMID 36143471, 2022). "ARHGDIB and STAT1 are increased in models of breast cancer CTCs while STAB1 and TLR2 are increased in tumor-associated inflammatory cells in breast and colorectal cancer." (PMID 36176417, 2022). "We have shown that OCT-1 knockdown suppresses the expression of the ARHGDIB, CAPZA2, PHACTR2, CDC42, XRCC5, and CAV1 genes, which is known to be increased in actively metastasizing breast cancer cells." (PMID 36143471, 2022). "ARHGDIB, RERG, and TMEM170B were also related to breast cancer, implying they might participate in the development of mammary glands." (PMID 36685960, 2022).
lung carcinoma (7 papers, 2013 to 2023). "On three large public available lung cancer datasets, the key drivers ARHGDIB and HOXD3 demonstrated significant associations with the overall survival of lung cancer patients." (PMID 25802847, 2015). "ARHGDIB was found to be a suppressor of the migration and invasion of human lung cancer." (PMID 35512017, 2022). "Also, ARHGDIB is reported to be involved in lung cancer tumorigenesis." (PMID 38016997, 2023).
prostate carcinoma (5 papers, 2014 to 2024). A carcinoma that arises from epithelial cells of the prostate gland. "The significant up-regulation of ROCK1 in cancers harboring the TMPRSS2:ERG fusion fits with an earlier report describing increased expression of ROCK’s upstream regulator Rho guanine diphosphate dissociation inhibitor beta (ARHGDIB) in ERG positive prostate cancers." (PMID 31557128, 2019). "Additionally, we show here that transcriptional co-repressor CtBP1, which has been shown to repress LCN2 (Lipocalin-2) and ARHGDIB (Rho GDP Dissociation Inhibitor Beta) expression in prostate cancer, regulates miR-124 expression." (PMID 25115393, 2014). "One notable exception was prostate cancer in which neither of the PGCC signatures but rather the 5-gene core signature of late progeny (FN1, INPP5D, ITGB4, ARHGDIB, IFIT1) was significantly predictive of outcomes." (PMID 38447798, 2024).
pancreatic cancer (4 papers, 2016 to 2021). "ARHGDIB is significantly up-regulated in pancreatic cancer cell." (PMID 33431999, 2021).
acute lymphoblastic leukemia (2 papers, 2020 to 2023). Leukemia with an acute onset, characterized by the presence of lymphoblasts in the bone marrow and the peripheral blood. "Pediatric acute lymphoid leukemia-phase II data from cBioPortal for cancer genomics reveals that RhoGDI2 gene ARHGDIB deep depletion is closely relative to the bone marrow site of relapse in B-ALL." (PMID 32903764, 2020).
HIV-1 infection (2 papers, 2019 to 2025). The type species of lentivirus and the etiologic agent of acquired immunodeficiency syndrome (AIDS). "It has been reported that elevated ARHGDIB was able to attenuate HIV-1 infection via negatively regulating the replication of HIV-1." (PMID 30897137, 2019).
breast tumor (1 paper, 2017). "To determine the potential clinical impact of RhoGDI2 on metastasization of HER2-amplified breast tumors, we examined mRNA expression of the gene encoding RhoGDI2, ARHGDIB, in publicly available HER2+ breast tumor datasets (N = 150, Kmplot.com)." (PMID 28666462, 2017).
glioma (1 paper, 2021). A benign or malignant brain and spinal cord tumor that arises from glial cells (astrocytes, oligodendrocytes, ependymal cells). "Among them, ARHGDIB, LRRC25, PLAUR, and TREM1 were selected as prognostic hub genes in lower grade glioma in previous bioinformatic analyses." (PMID 34858984, 2021).
Insulin resistance (1 paper, 2023). Increased resistance towards insulin, that is, diminished effectiveness of insulin in reducing blood glucose levels. "For example, the negatively associated protein ARHGDIA is a potent negative regulator of insulin sensitivity, and our fingerprint of insulin resistance contained its homologue ARHGDIB." (PMID 37494090, 2023).
peanut allergy (1 paper, 2021). "Both methods were used to generate human mAbs against peanut 2S albumins, major allergens in peanut allergy, and anti-Rho guanosine diphosphate dissociation inhibitor 2 (RhoGDI2, alternative and used ‘ARHGDIB’), a non-HLA target potentially involved in graft failure upon kidney transplantation." (PMID 34017336, 2021).
Sepsis (1 paper, 2023). Sepsis is defined as life-threatening organ dysfunction caused by a dysregulated host response to infection. "Firstly, for ARHGDIB, it was significantly downregulated in sepsis-induced ALI." (PMID 37700323, 2023). "It has been found in this research that the overexpression of ARHGDIB in sepsis-induced ALI increases the activity of immune cells, and ARHGDIB had a significant negative correlation with the regeneration of vascular endothelial cell." (PMID 37700323, 2023).
spastic ataxia (1 paper, 2025). "Because of the specific expression of PCP2 in Purkinje cells, we postulated that ARHGDIB and PCP2 are the critical target proteins related to ANKFY1 deficiency-induced spastic ataxia." (PMID 40594855, 2025).
cancer (37 papers, 2007 to 2025). A tumor composed of atypical neoplastic, often pleomorphic cells that invade other tissues. "Mounting evidence suggests that the reduced expression of ARHGDIB is associated with the development of several types of cancer and that its hypermethylation contributes to its reduced expression." (PMID 31516386, 2019). "Expression of ARHGDIB variants 6a, 6b, and 6c appears to be restricted to cancer cells and normal placental tissue, suggesting that these variants possess cancer-specific functions and, as such, are potential cancer-related biomarkers." (PMID 23206989, 2012). "Similar to the observation that KDM6A regulated ARHGDIB expression in a cancer-specific manner, among all four cell lines for different cancer types, the GSKJ4 treatment only inhibited ARHGDIB expression in HeLa and MKN-45 cells." (PMID 34006303, 2021). "Common differentially expressed genes SNCG and ARHGDIB were mostly found to be related to cancer, and they can regulate cell proliferation, differentiation, invasion, metastasis and other cell behaviors." (PMID 33676413, 2021). "ARHGDIB also known as RhoGDI2 has been identified as a proto-oncogene and is up regulated in multiple human cancer." (PMID 31303963, 2019). "In contrast, the mRNA expression of known ARHGDIB was ubiquitous in many normal tissues and cancer cells." (PMID 23206989, 2012). "ARHGDIB has been identified as a regulator of tumor metastasis, but its role in cancer remains unknown." (PMID 34184409, 2021). "Additionally, squamous morphology cancer cell lines aggregated by METHY patterns (C10 [ESCA-HNSC]), particularly in terms of ARHGDIB and SEPTIN9 loss." (PMID 32874774, 2020). "The number of selected genes by semi-supervised learning method is less than the single Cox and AFT model, but includes some genes which are significantly associated with cancer and cannot be selected by the two single Cox and AFT models, such as GDF15, ARHGDIB and PDGFRL." (PMID 26932592, 2016). "Although the Rho GDP dissociation inhibitor β (ARHGDIB) gene has been found to be ubiquitously expressed in normal tissues and involved in cancer development, the presence of splice variants of ARHGDIB has not yet been investigated." (PMID 23206989, 2012). "The overexpression of KDM6A only slightly increased the ARHGDIB levels in MKN-45 cells, indicating that KDM6A regulates ARHGDIB in a cancer type-specific manner." (PMID 34006303, 2021). "Genes related to B and T cell maturation (e.g. CD37, CD79B, JCHAIN, IGLL1, VPREB3, CD52), ribosomal protein genes (RPS-*, RPL-*) and cancer/stress genes (e.g. PRAME, ARHGDIB, FOS, JUN) were within the most significantly deregulated genes between clusters in those samples." (PMID 32415257, 2020).
tumor (34 papers, 2008 to 2025). "ARHGDIB expression is inversely associated with metastatic status and identified as an independent prognostic marker of tumour recurrence in BCa patients." (PMID 34006303, 2021). "The 6-protein diagnostic panel consisted of FLNA, PRDX6 and ARHGDIB, associated with tumor growth, cell invasion and metastasis, GSTO1, having an antioxidant defense role (together with PRDX6), TUBA4A, found enriched in serum exosomes from NSCLC patients, and the tumor suppressor CDH13." (PMID 32575471, 2020). "Functional role of Rho GDP-dissociation inhibitor beta (RhoGDIβ) in tumor biology appears to be contradictory across various studies." (PMID 37635218, 2023). "ARHGDIB has been identified as a critical inhibitor of Rho GTPases, through which ARHGIDB suppresses tumour metastasis." (PMID 34006303, 2021). "All five of the proteins predicted to be upregulated in EAC compared with normal esophagus (SAMHD1, ARHGDIB, AGR2, HSPA5, EPCAM) showed higher expression in the tumor sections compared with squamous epithelium." (PMID 28336725, 2017). "The ARHGDIB positive cells appeared, however, to be lymphocytes rather than epithelial-derived tumor cells." (PMID 28336725, 2017). "Indeed, among the most upregulated genes in FAT4 knockdown cells we found ARHGEF6, encoding for the guanine nucleotide exchange factor αPIX that activates Rac1 and Cdc42 GTPases and ARHGDIB, a negative modulator of the RhoA tumor suppressor." (PMID 39478125, 2024). "Although overall expression of ARHGDIB was indeed higher in EAC compared with normal squamous and gastric tissue, this staining was observed in stromal cells, most likely lymphocytes, rather than epithelial-derived tumor cells." (PMID 28336725, 2017).
infection (4 papers, 2011 to 2023). The state of being infected such as from the introduction of a foreign agent such as serum, vaccine, antigenic substance or organism. "ARHGDIB was found to show significant overexpression in COS-7 cells with the infection of enteropathogenic E. coli." (PMID 30897137, 2019). "Of those tested Cdc42ep3 (CDC42 effector protein), ARHGDIB (Rho GDP dissociation inhibitor (GDI) beta), Acta2 (Alpha actin 2), Egr2 (Early growth response 2), IL-6 (Interleukin 6) and Vav3 (vav 1 guanine nucleotide exchange factor), were induced by EPEC infection but not by infection with EPEC Δtir." (PMID 21490959, 2011).
ARHGDIB also shares sentences with these, for which no sentence is quoted: Hodgkins lymphoma (5 papers); osteosarcoma (4); colon cancer (3); ovarian carcinoma (3); hepatocellular carcinoma (2); lymph node metastasis (2); metastasis (2); non-small cell lung carcinoma (2); acute myeloid leukemia (1); adenocarcinoma (1); adenoma (1); Anxiety (1); asthma (1); autoimmune disease (1); basophilic leukemia (1); bladder tumors (1); calculus (1); cervical cancer (1); colorectal cancer (1); COVID-19 (1); fungal infection (1); gastric tumors (1); hypopharyngeal cancer (1); Infertility (1); inflammation (1); inflammatory bowel disease (1); kidney failure (1); leukemia (1); lung adenocarcinoma (1); melanoma (1).
A further 11 diseases each share a sentence with ARHGDIB in 1 paper.